CD4 (CD4 molecule)
Diseases named in the same sentence as CD4 in open-access papers (continued):
Sharing a sentence is not in itself a finding about the gene and the disease.
HIV-1 infection (continued). "Furthermore, most of our analyzed cell samples were collected during untreated HIV-1 infection, i.e., a considerably less well-studied period in regard to clonal expansion of latently HIV-1–infected CD4+ T cells, and thus, the dynamics of clonal expansion could be different in untreated individuals." (PMID 33784259, 2021). "Therefore, our research group investigated whether such non-apoptotic cell death is induced in CD4+ T cells in vivo during the early stage of HIV-1 infection." (PMID 33924786, 2021). "Unlike sCD4, CD4-IgG2 could not enhance HIV-1 infection in CD4- CCR5+ cells." (PMID 32523582, 2020). "Moreover, highly permissive and physiologically non-relevant HeLa-TZM-bl cells may not recapitulate the natural HIV-1 infection in CD4+ T cells." (PMID 31684192, 2019). "Indeed, HIV-1 infection was only significantly inhibited in GM-CSF macrophages (roughly 60% inhibition, p = 0.0019), whereas no change in HIV-1 susceptibility was seen in moDC or CD4+ T lymphocytes." (PMID 29042669, 2017). "Notably, increased CCR5 expression on blood and lung CD4 T cells in patients with tuberculosis with or without HIV-1 infection was proposed as a mechanism for the increased HIV viremia and hastened course of HIV progression associated with tuberculosis co-infection." (PMID 26762145, 2016). "Thus, among CD4-positive T cells, the TLR3 induced up-regulation of GPR15 expression is largely specific for gut homing CD4+ T cells and might broaden the target cell availability during HIV-1 infection in the gut." (PMID 24558379, 2014). "Long-term use of cART during chronic HIV-1 infection may increase numbers of memory and naïve CD4 T cells specific for opportunistic pathogens, but does not apparently allow regeneration of proliferative HIV-1-specific CD4 T-cell responses with the potential to keep the virus under control." (PMID 23459797, 2013). "For instance, it may be that the development of such antibodies during natural HIV-1 infection depends on the emergence of particular Env clones in certain HIV-infected subjects; clones with particular structural characteristics that allow them to engage the germline BCR form of bNAb to the CD4-BS." (PMID 23300456, 2013). "However, because their target is the HUT/CCR5 T cell line and culture conditions favor trans infection (immediate co-culture after HIV-1 infection), the question of whether cell surface expression of BST-2/tetherin assists or inhibits virus transmission to CD4+T cells via IS needs to be clarified." (PMID 23847602, 2013). "However, the frequency of Tim-3+CD8+ and Tim-3+CD4+ exhausted T cells, but not PD-1+ T cells, was significantly increased in the adolescents with longer duration of infection compared to the children with shorter duration of HIV-1 infection." (PMID 23029209, 2012). "In addition, cells expressing CXCR4Δ18 along with CD4 did not support HIV-1 infection." (PMID 21533216, 2011). "In fact, whether HIV-1 infection mechanistically affects apoptosis-related events in macrophages has not been tested, presumably because unlike CD4+ T cells undergoing cell death following G2 arrest, the cell death phenotype of HIV-1 infected macrophages is absent (these cells actually live longer)." (PMID 20927348, 2010). "Hence, to determine whether the restriction of cell-free HIV-1 infection is simply due to the lack of the main CD4 receptor, we previously transfected BeWo cells to obtain a CD4 expressing cell line which, however, also fails to sustain viral infection." (PMID 19445667, 2009). "The phenotype of these resting cells carrying a non-productive HIV-1 infection, derived from peripheral blood of patients undergoing antiretroviral therapy with low to undetectable viremia, indicates that they derive from infected CD4+ lymphoblasts that have reverted to a resting memory state." (PMID 16412247, 2006).
HIV-1 infection (continued). "SIVagm, SIVsmm, and SIVmac also use CD4 as the viral receptor and CCR5 as one of the main coreceptors, while CXCR4-tropic viruses are not as common as in HIV-1 infection." (PMID 39842407, 2025). "Second, in HIV-1 infection, long-term viremic non-progressors have significantly lower HIV burden in their CM CD4+ T cells than progressors." (PMID 41244297, 2025). "Further analysis confirms that these effects do not appear to be exclusive to MDDCs, as we also observe similar effects on HIV-1 infection when depleting these host factors in THP1 cells and Jurkat CD4-CCR5 cells, but not in primary CD4+ T cells." (PMID 40029073, 2025). "Unlike Langerin, DC-SIGN facilitates HIV-1 infection and transmission by abrogating TRIM5α restriction, allowing HIV-1 to evade degradation and be transferred to CD4+ T cells." (PMID 40029073, 2025). "It is a potent inhibitor of T-tropic HIV-1 infection both in HIV Rev-dependent indicator T cells (IC50 = 13 nM), PBMCs, and blood resting CD4 T cells, and was non-toxic to these cells at concentrations up to 50 μM." (PMID 39146384, 2024). "After HIV-1 infection, a strong positive correlation of IP-10 with HIV-1 RNA and a negative correlation with CD4+ T cell count has been reported." (PMID 37920466, 2023). "These conclusions are based on HIV-1 infection, irrespective of the env proteins (VSV-G or Env gene products), of two distinct cell types, heterologous HeLa cells and native primary CD4+ T cells." (PMID 37563144, 2023). "Unfortunately, we were not able to collect more data (CD4/CD8 count, course and stage of HIV-1 infection)." (PMID 35632613, 2022). "Our results showed that BMS-986158 moderately down-regulated the expression of the CXCR4 and CCR5 co-receptors in the CD4+ T cells, indicating that BMS-986158 does not increase potential de novo HIV-1 infection." (PMID 35337136, 2022). "We previously demonstrated that MDM comprised two populations: a non-adherent (CD14+CD4+Siglec-1hi) population refractory to HIV-1 infection and an adherent (CD14+CD4-Siglec-1 l°) population which was highly permissive to HIV-1 infection." (PMID 35534646, 2022). "Surprisingly, when CD4+ population was defined as CD3+ CD8−, the populations remain unalterable and do not present alterations compared to HIV-1 infection." (PMID 35307031, 2022). "Our studies provide direct evidence of CD4+ T cell infection in CSF during early acute infection in two independent models–macaque R5-tropic non-accelerated SHIV infection and human HIV-1 infection." (PMID 34874976, 2021). "Regardless of the route of HIV-1 infection, the virus quickly moves to GALT and rapidly replicates in part due to the high level of residential activated CD4+ T cells." (PMID 34879869, 2021). "The edited cells resisted R5-tropic HIV-1 infection but not X4-tropic HIV-1 infection compared with the control group in different cell types of HIV-1 study (TZM.bl, SupT1-R5, Primary CD4+T cells)." (PMID 32670545, 2020). "Inflammasome activation occurs during acute HIV-1 infection and persists in immune non-responders, patients on ART without CD4+ T lymphocyte recovery (CD4 < 350)." (PMID 32596261, 2020). "Since non-specific activation of CD4+ T cells can enhance FIV and HIV-1 infection, the selection of conserved protective peptide pools was based predominantly on CD8+ T-cell responses and to a lesser degree on CD4+ CTL activity." (PMID 30717485, 2019). "Because oligodendrocytes and neurons do not express the primary receptor (CD4) permissive for HIV-1 entry into cells, they are unlikely to host an HIV-1 infection." (PMID 32009881, 2019). "As a whole, the data show that levels of CD4+ cells were similar in NB-ZSG mice, irrespective of HIV-1 infection, suggesting that Nullbasic strongly protected CD4+ cell viability, which was evident at 31 dpi." (PMID 31455650, 2019). "For example, in HeLa-CD4 cells expressing high level of BST2, Vpu deletion did not enhance HIV-1 infection in one-step assay (unpublished data)." (PMID 31027334, 2019).
HIV-1 infection (continued). "This discovery provides further support for the notion that, as CD4+ T cells are the main targets of HIV-1 infection, they should contain miRNAs that are differentially expressed in the presence and absence of HIV-1 infection." (PMID 30619232, 2018). "The model can better differentiate recent HIV-1 infection from older infection than BED-CEIA and was not affected by gender, age, ART, and CD4+ T cell counts." (PMID 29568753, 2018). "ITK is not expressed in HEK293T or HeLa cells; however, if these cells are genetically modified to express CD4 and CXCR4, they are fully permissive for HIV-1 infection (data not shown)." (PMID 29453458, 2018). "Further analysis indicated that the percentage of both CD4+ and CD4- ILC1s in total CD45+ cells was lower in patients with HIV-1 infection than in the HC subjects, while only the CD4+ ILC1s but not CD4- ILC1s were significantly rescued by HAART." (PMID 29304123, 2018). "And, enhancement of HIV-1 infection by human α-defensins HD5 and HD6 is also independent of CD4 and co-receptors." (PMID 28622386, 2017). "Total CMV IgG was associated with higher CD4 T cell activation (HLA-DR+CD38+), and terminally differentiated (CD57+ and CD27−CD28−) CD4 and CD8 T cells in CMV-positive individuals irrespective of HIV-1 infection." (PMID 28806406, 2017). "Furthermore, recent studies highlight a strong relationship between HIV-1 infection and stage of breast cancer at diagnosis: more HIV+ women show an advanced tumor stage than general population, and this occurs in the absence of any association with viral load or CD4+ T cell count." (PMID 29021819, 2017). "HIV-1 p24+ CD8 negative Tem, that included DN and CD4 T cells, were characterized by higher expression of HLADR/CD38, Ki67, and CCR5, all of which are markers of successful HIV-1 infection of CD4 T cells." (PMID 27870882, 2016). "We focused on CD4+ T cells, the major cellular targets of HIV-1 replication in the GALT, but not intestinal macrophages, which are non-permissive to HIV-1 infection." (PMID 26529416, 2015). "The ability of B-cells to induce latent infection in non-proliferating CD4+ T-cells was also tested in this study as B-cells express MHC-II, circulate through LN, and have been reported to transfer HIV-1 infection to T-cells." (PMID 26362311, 2015). "IL-21 inhibited both R5- and X4-tropic HIV-1 infection, and did not alter surface expression of the HIV entry coreceptors CD4, CCR5 or CXCR4 on CD4 T cells, suggesting that the antiviral mechanism of IL-21 likely involved post-entry events." (PMID 26108174, 2015). "No significant quantitative differences in CD4+ and CD8+ T cell levels were observed between IDU and non-IDU subjects when accounting for the presence of HIV-1 infection." (PMID 26925299, 2015). "The HIV-1 replication did not occur also in CD4+ T lymphocytes from co-cultures carried out in the presence of AZT, thus ensuring that what we detected was consequence of authentic HIV-1 infection." (PMID 24924541, 2014). "To determine the relevance of RUNX1 expression in HIV-1 infection in human hosts we compared RUNX1 expression to viral load and CD4+ T-cell counts in viremic HIV-1 patients who were not on therapy." (PMID 24651404, 2014). "Overall, these data indicate that during HIV-1 infection, HLA-G-expressing CD8, but not CD4 T cells, are skewed to a more immature differentiation status, but this difference is not correlated to the rates of spontaneous HIV-1 disease progression." (PMID 23382678, 2013). "We found that ex vivo CD4+ T cells and CD8+ T cells, as well as HIV-specific CD8+ T cells from individuals with chronic HIV-1 infection are primed to undergo apoptosis through CD95/Fas but not TRAIL or TNFα signaling." (PMID 24130482, 2013). "Nucleotide depletion appears as a powerful mechanism of defense in quiescent cells that do not replicate their nuclear DNA, including CD4+ quiescent T cells, where SAMHD1 also restricts HIV-1 infection." (PMID 23497353, 2013).
HIV-1 infection (continued). "Taken together, these findings are consistent with a role for MPA in repressing systemic immune function by increasing apoptosis in CD4+ T-cells in the absence of HIV-1 infection, and an increase in this effect in the presence of HIV-1 infection." (PMID 23658782, 2013). "However, HEK293T cells, undifferentiated THP-1 cells and activated CD4+ T cells are not refractory to HIV-1 infection despite expressing SAMHD1, suggesting that the antiviral activity of SAMHD1 may be biologically important only in differentiated or non-dividing cells such as DC and macrophages." (PMID 24455433, 2013). "Despite readily detectable levels of the HIV-1 (co)-receptors CD4, CCR5 and DC-SIGN on placental macrophages (Hofbauer Cells [HCs]), the rate of HIV-1 infection in utero in the absence of interventions is only 7% of exposed infants." (PMID 23217137, 2012). "Therefore given that RA and HIV-1 infection are both characterized by inflammatory and immune hyperactivation conditions and considering the recently described link between RA and DCIR expression in CD4+ T cells, we hypothesized that HIV-1 can trigger DCIR expression in CD4+ T cells." (PMID 21085612, 2010). "Despite the presence of the CD4 molecule as well as CCR5 and CXCR4, no cell-free HIV-1 infection was detected in this cell line." (PMID 19445667, 2009). "After establishing the purity of the selected CD8+ T-cell population and demonstrating the absence of any contaminating CD4+ T-cells or Natural Killer (NK) cells (data not shown), the ability of CD8+ T-cells to support HIV-1 infection was ascertained." (PMID 18923697, 2008). "While MX2 depletion increased HIV-1 infection rates in single-round analyses in other cell types between 3- and 11-fold, our results suggest that MX2 is not a relevant HIV-1 restriction factor in resting CD4+ T cells." (PMID 34949807, 2022). "Indeed, Vpr causes G2 arrest and enhances HIV-1 gene expression in both primary CD4+ T cells and macrophages through the depletion of CCDC137, and a Vpr-mutant that is defective in G2 arrest is not able to augment HIV-1 infection in macrophages." (PMID 34835114, 2021). "Indeed, in HIV-1 infection, major disturbances have been described in the CD8+ TCRVβ repertoire, regardless of the clinical status, CD8+ and CD4+ T-cell counts, as well as viral load." (PMID 32508833, 2020). "At low concentrations (<1 μg/ml or 20 nM), sCD4 could not effectively inhibit HIV-1 infection, but rather enhanced the infection of some HIV-1 clinical isolates in host cells, including some CD4- CCR5+ cells." (PMID 32523582, 2020). "Additionally an immune checkpoint molecule, programmed cell death protein 1 (PD-1) is highly expressed on CD4+ and CD8+ T lymphocytes during HIV-1 infection, and does not fully normalize on ART." (PMID 32596261, 2020). "Thus, although many studies have indicated a role for Meth in exacerbation of HIV-1 infection, the full range of effects of Meth on HIV-1 replication in CD4+ T-cells is still not yet clear." (PMID 30700725, 2019). "The absolute cell counts of total ILC1s and CD4+ and CD4- ILC1s were found to be largely reduced in patients with chronic HIV-1 infection as compared to those of HC subjects; and HAART successfully recovered the absolute cell counts of total ILC1s and CD4+ ILC1s but not CD4- ILC1s." (PMID 29304123, 2018). "For HIV-1 infection, peripheral blood mononuclear cells (PBMCs) were isolated from buffy coats of healthy HIV negative donors using Ficoll density gradient (Eurobio) and CD4+ T-cells were isolated by negative selection (Stem Cell Research)." (PMID 29554134, 2018). "The experiments in in vitro cell cultures demonstrate that SAMHD1 restricts HIV-1 infection in non-dividing cells such as macrophages (plus phorbol 12-myristate 13-acetate-stimulated macrophage-like THP-1 cell line), DCs, and resting CD4+ T cells by degrading dNTPs." (PMID 29379496, 2017).
HIV-1 infection (continued). "The anti-HIV-1 activity of HD5 is likely artifact, since under serum-deprived conditions, HD5 blocked CD4 receptor-independent HIV-1 infection, attributable to an HD5-mediated increase in cell death in primary CD4+ T cells rather than a specific antiretroviral mechanism." (PMID 28505117, 2017). "Moreover, AAT also did not directly interact with CD4, CCR5, CXCR4 and other HIV-1 infection-related proteins." (PMID 27473095, 2016). "In the present study, we found that viral replication in AAT-pretreated CD4+ T cells was much lower than that in CD4+ T cells without AAT pretreatment, suggesting that AAT might exert its inhibitory effect on both HIV-1 infection and replication." (PMID 27473095, 2016). "Importantly, this model allowed for HIV-1 infection studies without the confounding effects of non-physiologic T cell activation, as HIV-1 can efficiently infect gut CD4+ T cells without exogenous mitogens." (PMID 26529416, 2015). "HIV-1 infection was equivalently suppressed by IL-21 even in the absence of NK, NKT and CD8 T cells, indicating that the observed antiviral activity of IL-21 did not depend on these cells but likely a direct effect on HIV-1 permissive CD4 T cells." (PMID 26108174, 2015). "Neopterin levels and the percentages of activated CD4+ and CD8+ T-cells in CSF progressively increase in most subjects without treatment during early HIV-1 infection, suggesting an accrual of intrathecal inflammation, a major contributor to neuropathology in HIV infection." (PMID 25465205, 2014). "These cells do not express CD4 or CCR5 and are resistant to HIV-1 infection." (PMID 25010677, 2014). "The frequency of the CM subset among human CD4+ T cells from uninfected hNOK/B51Tg mice gradually increased every 2 weeks, whereas that for the HIV-1-infected hNOK/B51Tg mice was not altered during the HIV-1 infection." (PMID 22880104, 2012). "D1D2 at the concentrations from 5 to 200 nM significantly enhanced the infection of the virus in the CD4-/CCR5+ cells, while 2DLT and T1144 at the same concentrations showed no enhancement of HIV-1 infection, suggesting that 2DLT exhibits no enhancing effect on HIV-1 infectivity in CD4-/CCR5+ cells." (PMID 23217195, 2012). "One possible explanation is that a small fraction of CD4 and CXCR4 on PBMCs, but not on MT4 cells, are sufficient for HIV-1 infection; as a result, partial down regulation of CD4 and CXCR4 potently inhibits HIV-1 infection of MT4 cells but is not effective against ×4 virus infection of PBMCs." (PMID 22039528, 2011). "CD4+ T cells, the main cells of HIV-1 replication, are not ‘professional primers’ of CD8+ T cells (although are likely to expand already primed responses) and many, if not most, T cell responses in natural HIV-1 infection must be initiated by cross-priming." (PMID 21625575, 2011). "However, despite a functional CD4 receptor and the endogenously expressed CCR5 and CXCR4 co-receptors, cell-free HIV-1 infection was still restricted in BeWo-CD4+ cells (data not shown)." (PMID 19445667, 2009). "In summary, our results demonstrate that CD4+ TEMRA cells are present at a higher frequency in HIV-infected than uninfected individuals and are resistant to R5-tropic HIV infection, but not to X4-tropic HIV-1 infection." (PMID 17465678, 2007). "The result revealed that after a 30 min incubation period during which the mixtures three separate mixtures (HIV-1 plus crude saliva), (HIV-1 plus MUC5B) and (HIV-1 plus MUC7) were incubated with the CD4+ CEM SS cells, no HIV-1 infection of these cells was observed." (PMID 17125499, 2006). "HIV-2 infected cells do not seem to resist subsequent HIV-1 infection, which may be explained by the inability of HIV-2 to induce CD4 down-modulation." (PMID 16107223, 2005). "Therefore, in CD4+ T cells, our findings suggest that IFN-α may not strongly induce an antiviral effect, but rather, promotes cell-free HIV-1 infection when V/C is high." (PMID 35468127, 2022).